KLF5 (KLF transcription factor 5)
Diseases named in the same sentence as KLF5 in open-access papers (continued):
Sharing a sentence is not in itself a finding about the gene and the disease.
cancer (194 papers, 2009 to 2026). A tumor composed of atypical neoplastic, often pleomorphic cells that invade other tissues. "Elevated KLF5 levels have been associated with adverse outcomes in HF, diabetic cardiomyopathy, vascular disease, and cancer, underscoring its central role in cellular stress responses." (PMID 41526530, 2026). "We investigated the clinical characteristics, prognostic significance, mutations, and methylation patterns of KLF5 across various cancer types." (PMID 41583492, 2025). "By mapping its genomic alteration spectra, expression profiles, and associated clinical outcomes across the cancer spectrum, we can delineate a definitive functionality map for KLF5." (PMID 41583492, 2025). "Based on the preceding pan-cancer analysis, we investigated the potential of KLF5 as a diagnostic or prognostic biomarker in specific tumors." (PMID 41583492, 2025). "The association between KLF5 and cancer is controversial, given that, depending on the experimental conditions, it can either promote cell migration and invasion or inhibit cancer progression by preventing EMT." (PMID 41443421, 2025). "In conclusion, our integrated analysis of scRNA-seq and metastatic scoring data reveals the opposing roles of SP1 and KLF5 in regulating metastasis by governing the underlying gene expression program in cancer cells." (PMID 39748426, 2025). "A known cancer variant rs9600079 approximately 76 kb downstream from KLF5 showed slight association (P = 0.0017)." (PMID 38052806, 2023). "When assessing low and high-grade PDAC tumors, KLF5 mRNA and protein expression consistently increased at higher grades, indicating an association with greater cancer aggressiveness and poor prognosis." (PMID 37239940, 2023). "Research on the cancer transcriptome has sought to narrow our understanding of KLF5 association with PDAC found in genome-wide analyses." (PMID 37239940, 2023). "It has been reported that KLF5 overexpression played a significant role in the self-renewal ability of cancer stem cells and was associated with stemness." (PMID 36042208, 2022). "Klf5, the most downregulated TF, is an active factor associated with miRNAs in cancer and cardiovascular disease." (PMID 36203804, 2022). "This study reported three modes of action for KLF5 activation in cancer and noted that one of these functions was mediated by cancer type-specific mutations enriched in the zinc-finger motif." (PMID 31925297, 2020). "Since Wnt signalling is associated with cancer stemness, it is of interest that KLF5 can strengthen β-catenin activity by facilitating its nuclear localisation." (PMID 32066912, 2020). "The increased proliferation seen in PAH-PASMC is associated with a KLF-5-dependent up-regulation of cyclin B1, confirming previous findings in systemic vessels and cancer." (PMID 21951574, 2011). "Additionally, the correlation analysis demonstrated that KLF5 CNV alterations were associated with a widespread positive correlation with its mRNA expression across most cancer types." (PMID 41583492, 2025). "KLF5 is significantly linked to various malignant pathways across different types of cancer." (PMID 41583492, 2025). "This work also identifies KLF5 as a potential target for treating ARID1A-deficient cancers." (PMID 39779698, 2025). "Overall, our work identifies KLF5 as a potential target for eradicating ARID1A-deficient cancers." (PMID 39779698, 2025). "DeAc-KLF5 upregulates CX3CR1 to enhance FGFR1 activation in PTEN-deficient cancer cells." (PMID 38781024, 2024). "KLF5 has been associated with cancer cell invasion, migration and angiogenesis." (PMID 33430300, 2021). "However, a later study revealed that the nuclear staining of KLF5 was associated with more advanced cancer and poorer survival." (PMID 33923166, 2021).
cancer (continued). "KLF5 overexpression has been associated with stemness and self-renewal of cancer stem cells." (PMID 33424607, 2020). "KLF5 has been associated with cancer cell invasion, migration and EMT progression." (PMID 33424607, 2020). "Moreover, a recent study reports that the somatic mutation c.910C>A (p.P304T) position of KLF5 was reported as the hotspot of mutations in the phosphor–degron domain, which promotes cancer cell proliferation." (PMID 31336886, 2019). "Additionally, the assessment of the KLF5 mutation landscape in a pan-cancer context demonstrated that missense mutations were the most prevalent overall, yet the mutation types differed among specific cancer types." (PMID 41583492, 2025). "Krüppel-like factor 5 (KLF5) is an intrinsically disordered transcription factor involved in cardiac remodeling, cancer, and metabolic diseases." (PMID 41526530, 2026). "A comprehensive cancer survival analysis demonstrated a strong correlation between KLF5 expression and patient prognosis, underscoring its role as a prognostic biomarker." (PMID 41583492, 2025). "We find that recurrent somatic mutations in conserved enhancer regions largely correspond to those associated with known transcription factors with a role in pancreatic development and cancer, including KLF5 and TP63." (PMID 40971319, 2025). "Investigation into the post-translational modifications (PTMs) identified the significant fold change of KLF5 methylation values across pan-cancer." (PMID 41583492, 2025). "Transcription factors TP63, SOX2, and KLF5 have been demonstrated to influence chromatin dynamics and contribute to cancer-specific gene ALDH3A1 inactivation in ESCC." (PMID 40523880, 2025). "Cellular localization of KLF5 expression was analyzed using the TISCH2 pan-cancer scRNA-seq database, where it was found to be predominantly enriched in malignant and epithelial cells." (PMID 41583492, 2025). "In this study, we discovered that KLF5 was highly expressed in PDAC and closely associated with cancer progression." (PMID 39827156, 2025). "KLF5 is a transcriptional activator that is often used as a therapeutic target and prognostic marker for cancer." (PMID 40781327, 2025). "KLF5 transcription levels are elevated in the majority of cancer types, as revealed by transcriptomic analysis across various cancer cell lines." (PMID 41583492, 2025). "In contrast, KLF5 is a critical dependency in multiple carcinomas, as shown in both human cancer cell lines and genetic mouse models." (PMID 41241675, 2025). "SP1 acts as a driver of metastasis, while KLF5 functions as a suppressor across multiple cancer types at defined time points of the metastatic transition." (PMID 39748426, 2025). "These intriguing findings shed light on the complex and context-dependent roles of SP1 and KLF5 in cancer metastasis." (PMID 39748426, 2025). "Krüppel-like factor 10 (Klf10) has been described as regulators of muscle wasting in cancer (cachexia), and Klf5 was upregulated in atrophying myotubes as an early response to dexamethasone or simulated microgravity in vitro." (PMID 40649857, 2025). "Analyses based on TCGA database in the pan-cancer clinical prognostic significance of KLF5 were then performed." (PMID 41583492, 2025). "In ESCA, ALDH3A1 is regulated by the core regulatory circuitry transcription factors TP63, SOX2 and KLF5 and is involved in the proliferation of cancer cells." (PMID 40529228, 2025). "Bubble plot illustrating the correlation between KLF5 mRNA expression and DNA methylation levels in various cancers, particularly in PAAD, UVM, THYM, KIRP, BLCA." (PMID 41583492, 2025).
cancer (continued). "Intriguingly, many other transcription factors are also among the differentially regulated genes in the Kl5KD, including those involved in the immediate early stress gene regulation, postulated to be upstream of Klf5 in cancer and other cells." (PMID 40250760, 2025). "This is interesting because Cyclin D1 is a downstream target gene of Kruppel‐like factor 5 (KLF5), which is up‐regulated in cancer due to Wnt signaling in an 8‐catenin‐dependent way." (PMID 41179371, 2025). "To measure the expression patterns among the overall cell populations in PDAC, we reanalyzed two published single-cell RNA-sequencing dataset in PDAC patients, and found that KLF5 was expressed at its highest level in cancer cells." (PMID 39827156, 2025). "We conducted a comprehensive pan-cancer analysis of KLF5, examining its expression, prognostic impact, genomic alterations, post-translational modifications, and functional roles across multi-omics datasets." (PMID 41583492, 2025). "We were particularly interested in two TFs, SP1 and KLF5, given their previous implications in cancer metastasis and opposite kinetics in our data during metastasis progression." (PMID 39748426, 2025). "Studies utilizing multi-omics datasets to systematically investigate the role of KLF5 expression in pan-cancer contexts are still limited." (PMID 41583492, 2025). "Further characterization of specific methylation sites will help elucidate the regulatory role and functional impact of KLF5 methylation in pan-cancer contexts." (PMID 41583492, 2025). "Through functional perturbation, we identified SP1 and KLF5 as crucial regulators, acting as drivers and suppressors of metastasis, respectively, across multiple cancer types." (PMID 39748426, 2025). "Subsequent IHC results confirmed that KLF5 was expressed at higher levels in PDAC tissues than in para-carcinoma tissues." (PMID 39827156, 2025). "We, therefore, propose that KLF5 contributes to the uniquely variable pattern of chr13q aneuploidy across cancer types." (PMID 38622679, 2024). "Intriguingly, the DANCR lncRNA is activated by the KLF5 master regulator in GC, known to undergo genomic amplification in this form of cancer." (PMID 39456519, 2024). "While KLF5 is acknowledged to hold a significant role in various cancers, its role in bone diseases remains largely unexplored." (PMID 39161535, 2024). "A follow-up study showed the KLF5 SE is focally amplified in numerous different cancers, albeit at low frequency, with increased dependency of cancer cells on KLF5 expression." (PMID 37415185, 2023). "In conclusion, the present findings decipher the effect of KLF5-induced PGE2 generation modulation on cancer immune escape, highlighting an immunostimulatory role of KLF5 inhibitors for cancer therapy." (PMID 36923542, 2023). "The KLF5 transcription factor, an oncogene implicated in several cancers including CRC, exhibits hotspot E419Q mutations in its DNA binding domain results in over 5000 gained binding sites compared to WT KLF5 including de novo SEs at pro-tumorigenic genes." (PMID 37415185, 2023). "In our study, we have also identified KLF5 as a YAP1 tyrosine phosphorylation-dependent interacting transcriptional factor to mediate SRC activation-enhanced cancer stemness and metastasis in TNBCs." (PMID 36633714, 2023). "The last decade has brought much information regarding the roles KLF4 and KLF5 play in cancer development and progression." (PMID 37173904, 2023). "Its expression was predominantly increased in cancer cells, and a subset of these highly expressed KLF5 cells appeared to coincide with those cells having relatively high MLK4 expression." (PMID 37407566, 2023). "Previous studies have shown that TGF-β relies on the acetylation of a transcription factor called KLF5 at position K369 to regulate various biological processes, including cancer cell spread to the bone." (PMID 38260135, 2023).
cancer (continued). "Human kruppel-like factor 5 (KLF5) is an important transcription factor that regulates cell proliferation, differentiation, cell cycle regulation, and angiogenesis and suppresses cancer cell growth." (PMID 38129384, 2023). "Understanding the context-dependent functions of KLF4 and KLF5 and the mechanisms through which they exert their effects will be extremely helpful in developing targeted cancer therapy." (PMID 37173904, 2023). "Second, in vivo experiments should be performed to validate the roles of KLF5 in cancer proliferation, migration, and invasion." (PMID 38087142, 2023). "KLF5, on the other hand, uses the NF-κB pathway to develop cancers such as thyroid and laryngeal carcinomas." (PMID 36761967, 2023). "Among the candidates was KLF5, that has been shown to promote cancer cell proliferation in various cancers." (PMID 37377893, 2023). "This study revealed that increased ketogenesis suppressed KLF-5 dependent CXCL12 signaling, which is implicated in the growth and metastasis of cancer cells." (PMID 37692839, 2023). "Recent studies have demonstrated a regulatory relationship between KLF5 and SEs in several types of cancer." (PMID 37702443, 2023). "We recently reported that in basal-like breast cancer (BLBC) cells, YB-1 promotes KLF5 expression and cancer cell proliferation." (PMID 35406781, 2022). "The work presented here indicates that KLF5 plays an important role in α-Catulin-driven cancer stemness." (PMID 35154481, 2022). "As a DNA-binding transcription factor, KLF5 has been shown in previous studies to promote cancer cell proliferation and apoptosis resistance in different human cancers." (PMID 35154481, 2022). "We recently reported in BLBC cells that YB-1 also recognizes and stabilizes m5C-modified KLF5 mRNA to promote cancer cell proliferation." (PMID 35406781, 2022). "It is now accepted that KLF5 is a short-lived protein that can be rapidly degraded by the ubiquitin-proteasome system in cancer cells." (PMID 35154481, 2022). "To investigate the functional relevance of the KLF5 enhancer in cancer stem-like properties, we examined the chemoresistance, sphere-formation ability and expression level of CSC-related genes in heterodeletion mutants of the KLF5 enhancer." (PMID 34707247, 2022). "Our data also show a potential role of KLF5 in the regulation of cancer-stem-cell-like cells in PTC." (PMID 33430300, 2021). "To investigate androgen-independent mechanisms regulating KLF5 upregulation in CRPC, we evaluated a super-enhancer of the KLF5 gene that displays genomic duplication and active chromatin marks in cancers where KLF5 is oncogenic." (PMID 34737261, 2021). "In terms of cancer-driven mutations, the HRSI group has two significant mutations, including HRAS and KLF5, while the LRSI group has three significant mutations, including ATP6V0A2, BSX, and VNN1." (PMID 34504628, 2021). "Interactions between KLF5 and HIF-1α have also been widely reported in cancers that KLF5 is upregulated and induces cell proliferation and angiogenesis." (PMID 33493334, 2021). "Apart from Cdkn1c, other cancer-related genes, such as RASSF7 and GPRC5A has also been linked with Klf5 in this study." (PMID 33923166, 2021). "KLF5 is a zinc-finger transcriptional factor that plays an important role in cell transformation, cancer stemness, angiogenesis and migration." (PMID 33430300, 2021). "Second, we found that a KLF5 super-enhancer active in other cancers displayed a high density of active chromatin marks in PC-3 cells and that KLF5 expression in PC-3 cells was insensitive to AR re-expression." (PMID 34737261, 2021). "KLF5 regulates a number of cellular functions and can play a part in a variety of diseases, such as cancer, cardiovascular disease and gastrointestinal disorders." (PMID 33523554, 2021).
cancer (continued). "Supporting previous findings that super-enhancers play important roles in cell identity and cancer hallmarks, we observed super-enhancers associated with several known GC oncogenes, such as MYC, KLF5, and EGFR." (PMID 34635154, 2021). "Knock down of KLF5 suppresses the resistance to anti-cancer cisplatin in lung cancer cells, through inactivation of the PI3K/Akt/mTOR pathway." (PMID 33573362, 2021). "Collectively, these data point to KLF5 having divergent effects on cancer phenotypes, which are likely influenced by AR levels, epithelial cell identity, KLF5 levels, KLF5 acetylation, and hormonal milieu, among other factors." (PMID 34737261, 2021). "As the function of KLF5 is content-dependent, we need to study KLF5 in a case-by-case manner in different cancer types." (PMID 33923166, 2021). "High expression of KLF5 can promote cancer progression, such as the increase in KLF5 can promote breast cell proliferation and tumorigenesis." (PMID 34367275, 2021). "In vitro studies demonstrated that PVT1 expression drives cancer cell proliferation through promotion of the KLF5/BAP1/beta‐catenin signalling pathway." (PMID 32058674, 2020). "Another convincing case is the transcription factor KLF5, which has been experimentally validated as a cancer driver gene in a recent publication." (PMID 31925297, 2020). "Krupple-like factor 5 (KLF5), a zinc-finger transcriptional factor, is highly expressed in a variety of cancer types." (PMID 33424607, 2020). "More recently, our and other groups have reported that pharmacological inhibition of KLF5 by various inhibitors significantly suppressed cancer cell growth and/or survival." (PMID 32025209, 2020). "KLF5 expression and activity are altered in many cancer types including breast, cervical, colorectal, lung, pancreatic and thyroid cancer." (PMID 33424607, 2020). "KLF5 is a member of the Kruppel-like factor, subfamily of zinc finger proteins that are involved in cancers." (PMID 32943987, 2020). "Among the various transcription factors that regulate p27Kip1, KLF5 directly regulates p27Kip1 mRNA levels and induces cancer cell proliferation." (PMID 30770784, 2019). "Based on its implications in various signaling pathways and cancers, KLF5 has become a therapeutic target for cancer therapy development." (PMID 31083655, 2019). "KLF5 dysregulation has been studied in various cancer types; however, to our knowledge, our study is the first to examine KLF5 in EAC." (PMID 31401336, 2019). "We examined a cohort of BRAF‐wild‐type cancers and BRAF‐mutant cancers, further stratified by microsatellite instability status, and found KLF5 to be significantly elevated in BRAF‐mutant cancers." (PMID 30478887, 2019). "The three most frequently gained loci in the whole data set were HNF4A in 803 or 47% of 1699 cancers, KLF5 (709 or 42%) and MYC (585 or 34%), all of which have previously been implicated as amplification targets in CRC8,13,14." (PMID 30202008, 2018). "More importantly, pharmacological inhibition of KLF5 by various inhibitors significantly suppressed cancer cell growth and/or survival." (PMID 29348684, 2018). "Mechanistically, they show that TGFβ induces the expression of Sox4 in a Smad4-independent manner that then cooperates with the epithelial lineage determinant Kruppel like factor 5 (Klf5) to promote oncogenic growth in KrasG12D-driven cancers." (PMID 28649369, 2017). "KLF5 has been reported to exert pro-oncogenic activity by regulating gene transcription and stimulating cancer cell progression." (PMID 29146991, 2017). "We recently reported that mifepristone inhibits KLF5 expression and cancer stem cells in basal TNBC." (PMID 28437471, 2017). "In univariable logistic regression analysis, copy number gains in KLF5 (hazard ratio (HR): 3.2; 95% confidence interval (CI): 1.2–9.1; p = 0.025) and ZFHX3 (HR: 2.5; 95%CI: 1.1–6.0; p = 0.038) were associated with cancer-specific mortality." (PMID 28915599, 2017).